SSC5D (scavenger receptor cysteine rich family member with 5 domains)
Description:
Binds to extracellular matrix proteins. Binds to pathogen-associated molecular patterns (PAMPs) present on the cell walls of Gram-positive and Gram-negative bacteria and fungi, behaving as a pattern recognition receptor (PRR). Induces bacterial and fungal aggregation and subsequent inhibition of PAMP-induced cytokine release. Does not possess intrinsic bactericidal activity. May play a role in the innate defense and homeostasis of certain epithelial surfaces (By similarity).
Synonyms: FLJ35258; S5D-SRCRB
Tractability: Antibody: UniProt places it where antibodies can reach, with medium confidence; UniProt predicts a signal peptide or a membrane-spanning region; its Gene Ontology location is reachable by antibodies, with medium confidence.
Gene: Protein-coding gene on chromosome 19 (55,488,404 to 55,519,099, forward strand). Ensembl gene ENSG00000179954.
Subcellular location: Secreted; Cytoplasm
Subcellular location (Human Protein Atlas): Cytosol; Nucleoplasm; Predicted to be secreted
Pathways (Reactome):
Vesicle-mediated transport: Scavenging by Class B Receptors
Gene Ontology:
Molecular function: protein binding; extracellular matrix binding; fibronectin binding; laminin binding; scavenger receptor activity
Biological process: defense response; detection of bacterial lipoprotein; negative regulation of interleukin-8 production; defense response to Gram-negative bacterium; defense response to Gram-positive bacterium; vesicle-mediated transport
Cellular component: extracellular matrix; extracellular region; cytoplasm; membrane
Genetic constraint (gnomAD): Loss-of-function variants: 104 observed, 96.72 expected, observed/expected ratio (o/e) 1.08, 90% interval 0.92 to 1.27. The upper end of that interval is the gene's LOEUF score, 1.27, which puts it in group 5 of 6, group 1 being the genes least tolerant of losing a copy. Missense variants: 1,900 observed, 2,009.3 expected, observed/expected ratio (o/e) 0.95, 90% interval 0.91 to 0.98. Synonymous variants: 825 observed, 822.71 expected, observed/expected ratio (o/e) 1, 90% interval 0.95 to 1.06.
Homologues: Orthologues: chimpanzee SSC5D (97% identical), macaque SSC5D (94% identical), dog SSC5D (74% identical), pig SSC5D (74% identical), rat Ssc5d (67% identical), mouse Ssc5d (64% identical), zebrafish si:dkey-14d8.20 (16% identical), Drosophila melanogaster Loxl2 (7% identical), zebrafish si:ch211-150o23.3 (5% identical). Paralogues in human: DMBT1 (23% identical), CD163 (19% identical), SCART1 (18% identical), CD163L1 (18% identical), PRSS12 (14% identical), SSC4D (12% identical), LOXL4 (12% identical), LOXL2 (11% identical), LOXL3 (11% identical), CD5L (10% identical), CD6 (9% identical), CD5 (7% identical), and 3 more.
Diseases named in the same sentence as SSC5D in open-access papers:
SSC5D is named in the same sentence as 4 diseases in open-access papers, as found by Europe PMC text mining. Sharing a sentence is not in itself a finding about the gene and the disease. The quoted sentences say what the papers report.
myocardial infarction (1 paper, 2023). Gross necrosis of the myocardium, as a result of interruption of the blood supply to the area, as in coronary thrombosis. "Quantitative real-time polymerase chain reaction assay was used to quantify Ssc5d mRNA levels in murine heart tissue after myocardial infarction and transverse aortic constriction surgery." (PMID 37123263, 2023). "In a murine model of myocardial infarction or transverse aortic constriction, Ssc5d mRNA levels were markedly increased compared with those in the sham group." (PMID 37123263, 2023).
osteoarthritis (1 paper, 2014). A noninflammatory degenerative joint disease occurring chiefly in older persons, characterized by degeneration of the articular cartilage, hypertrophy of bone at the margins and changes in the synovial membrane. "Proteins such as CD5 molecule-like protein (CD5L), soluble scavenger receptor cysteine-rich domain-containing protein (SSC5D), and TTK protein kinase (TTK) were found to be upregulated in the synovial fluid of osteoarthritis patients." (PMID 24393543, 2014).
SSC5D also shares sentences with these, for which no sentence is quoted: heart failure (1 paper); liver fibrosis (1).